CPT1A (carnitine palmitoyltransferase 1A)
Diseases named in the same sentence as CPT1A in open-access papers (continued):
Sharing a sentence is not in itself a finding about the gene and the disease.
colon cancer (26 papers, 2010 to 2025). "CPT1A upregulation is a key metabolic alteration that cancer cells use to promote β-catenin acetylation and activation, while knockdown of CPT1A can reduce the expression of genes linked with colon cancer cells downstream of Wnt/β-catenin." (PMID 37033619, 2023). "In addition, CPT1A-dependent FAO might be a key metabolic pathway that associates adipocytes to colon cancer cells." (PMID 34764874, 2021). "CPT1A is a key regulator that connects the adipocyte-mediated regulation of cellular metabolism to WNT signalling in colon cancer cells." (PMID 38654238, 2024). "CPT1A was proposed to be a key regulator linking fatty cell-mediated cell metabolism regulation to WNT signal transduction in colon cancer cells." (PMID 38654238, 2024). "Carnitine palmitoyltransferase 1A (CPT1A) is an essential enzyme in FAO whose overexpression has been reported in colon cancer cells and tissues." (PMID 39355533, 2024). "Colon cancer develops in adipose-rich microenvironment, and CPT1A overexpression is crucial for adipocytes to promote tumor growth in colon cancer." (PMID 37033619, 2023). "These exosomes increased the sensitivity of colon cancer cells to oxaliplatin by downregulating CPT1A." (PMID 35765040, 2022). "Recently, CPT1A-siRNA was loaded into exosomes and surface modification with iRGD was performed to promote their selectivity toward colon cancer cells." (PMID 35765040, 2022). "In this study, CPT1A was found to be highly expressed in colon cancer tissues compared with adjacent tissues." (PMID 34213835, 2021). "Remarkably, upregulation of CPT1A in CAFs promotes the proliferation and invasion of colon cancer by enhancing the ability of CAFs to secrete CCL2, VEGF‐A, and MMP2." (PMID 33528867, 2021). "Second, this study explored the potential correlation between CPT1A and oxaliplatin resistance in colon cancer." (PMID 34213835, 2021). "iRGD‐exo‐si showed greater suppression of CPT1A than exo‐si in vitro and in vivo, which suggested that iRGD exosome was a superior candidate for specific siRNA delivery to colon cancer." (PMID 34213835, 2021). "We first confirmed the expression of CPT1A in 13 pairs of colon cancer tissues, and it showed higher levels in cancer tissue." (PMID 34213835, 2021). "Here, we showed that cancer‐associated fibroblasts (CAFs) promote the proliferation, migration, and invasion of colon cancer cells via upregulating CPT1A to actively oxidize FAs and conduct minimal glycolysis." (PMID 33528867, 2021). "In metabolically challenging tumor microenvironment, cancer‐associated fibroblasts (CAFs) enhance fatty acid catabolism by upregulating CPT1A expression and drive colon cancer peritoneal metastasis." (PMID 33528867, 2021). "This study provides new knowledge of the role of lipid catabolism in the intercommunication of tumor and immune cells, which can be extrapolated to other cancers with high CPT1A expression like breast, ovarian, and colon cancers." (PMID 33352903, 2020). "Results from our study here provide strong evidence supporting a role of CPT1A in controlling the production of signaling metabolites to mediate the communication between adipocytes and colon cancer cells." (PMID 32913185, 2020). "To this end, we determined the expression of CPT1A in tumor specimens obtained from stage IV colon cancer patients." (PMID 32913185, 2020). "Taken together, our results demonstrate that uptake of fatty acids renders colon cancer cells resistant to nutrient deprivation and this acquired survival advantage relies on CPT1A-mediated FAO." (PMID 32913185, 2020). "In summary, results from our study identify CPT1A as a key regulator that connects adipocyte-mediated regulation of cellular metabolism to Wnt signaling in colon cancer cells." (PMID 32913185, 2020). "The CPT1A expression was markedly increased in the presence of adipocytes as measured by quantitative RT-PCR in colon cancer cells and Western blotting analysis." (PMID 32913185, 2020).
colon cancer (continued). "In subsequent experiments, OA or PA was used to examine CPT1A-dependent effects in colon cancer cells." (PMID 32913185, 2020). "Using primary colon cancer cells, 3D tumor organoids and in vivo xenograft models, we showed that uptake of fatty acids promotes the expression of CPT1A through the activation of PPARδ." (PMID 32913185, 2020). "Similar results were obtained using OA as the metabolic substrate in Seahorse measurements to confirm that knockdown of CPT1A decreases FAO in colon cancer cells." (PMID 32913185, 2020). "Silencing CPT1A expression in colon cancer cells blocks the cell survival advantage provided by adipocytes as a result of decreased fatty acid degradation via FAO." (PMID 32913185, 2020). "Furthermore, increased CPT1A expression has been observed in various cancers, such as breast, prostate, glioblastoma, leukemia, and colon cancers." (PMID 40718711, 2025). "Overall, CPT1A inhibition may be a useful strategy to lessen the promotion impact of adipocytes on colon cancer." (PMID 37033619, 2023). "Moreover, iRGD exo-si showed stronger CPT1A inhibition than exo-si both in vitro and in vivo, suggesting that iRGD-modified exosomes are a better candidate for siRNA targeting colon cancer." (PMID 37553810, 2023). "Researchers have identified CPT1A as a potential target for colon cancer treatment." (PMID 35359956, 2022). "Emerging studies have suggested the enhancement of FAO inhibits the proliferation of colon cancer cells, and CPT1A is a key enzyme responsible for FAO, raising speculation that SIN inhibited tumor cell proliferation via CPT1A." (PMID 36295848, 2022). "Moreover, the inhibitory effect of SIN on the proliferation of human colon cancer cells was blunted via CPT1A inhibitor." (PMID 36295848, 2022). "Silencing CPT1A by siRNA or etomoxir, a specific small‐molecule inhibitor of CPT1A, could reverse the sensitivity of drug‐resistant colon cancer cells to oxaliplatin." (PMID 34213835, 2021). "In conclusion, iRGD‐exo‐si showed enhanced efficiency in knocking down CPT1A compared with control‐exo‐si, which might provide a new method for delivery of siRNA targeting for colon cancer." (PMID 34213835, 2021). "Here, we confirmed that CPT1A was heterogeneously expressed in colon cancer cells, with a high expression in oxaliplatin‐resistant cells but low expression in oxaliplatin‐sensitive cells, and expression could be increased by oxaliplatin stimulation." (PMID 34213835, 2021). "A second study found that carnitine palmitoyltransferase I (CPT1A), an enzyme necessary in the beta-oxidation of long chain fatty acids, was upregulated in colon cancer cells exposed to adipocytes, while silencing of CPT1A eliminated the protective effect provided by adipocytes in vitro and in vivo." (PMID 33498240, 2021). "More importantly, the results showed that the expression of CPT1A increased significantly after oxaliplatin stimulation, which implied that CPT1A might be a vital target to reverse oxaliplatin resistance in colon cancer." (PMID 34213835, 2021). "CPT1A expression is increased in various cancers, including prostate, ovarian, glioblastoma, lymphoma, breast, gastric, and colon cancers; however, it is hard to discern CPT1A expression and activity in the hypoxic regions of the tumor using the available clinical samples." (PMID 34944922, 2021). "Taken together, our results suggest that downregulation of CPT1A impairs FAO in colon cancer cells." (PMID 32913185, 2020). "Blocking CPT1A with iRGD‐exo‐si sensitized cells to oxaliplatin with low toxicity and high tumour‐targeting ability, which not only provided an effective approach to treat colon cancer that is oxaliplatin resistant but also propelled the application of siRNA in the clinic." (PMID 34213835, 2021).
colon cancer (continued). "Next, exosomes were cocultured with colon cancer cells, and it was confirmed by quantitative reverse transcription‐polymerase chain reaction (qRT‐PCR) and western blot that iRGD‐exo‐si significantly downregulated the expression of CPT1A more efficiently than control‐exo‐si (exo‐si)." (PMID 34213835, 2021). "Nevertheless, whether CPT1A is correlated with oxaliplatin resistance in colon cancer is unclear." (PMID 34213835, 2021). "To further confirm this hypothesis, we checked the IC50 of cells directly after silencing CPT1A with siRNA or etomoxir and it showed that blocking CPT1A reversed oxaliplatin resistance in colon cancer, which could be a novel method for reversal of oxaliplatin resistance." (PMID 34213835, 2021). "Finally, we designed iRGD‐engineered exosomes to transport CPT1A siRNA specifically to colon cancer cells and tumours, which might efficiently silence CPT1A and serve as a potential carrier to reverse oxaliplatin resistance in drug‐resistant colon cancer." (PMID 34213835, 2021). "Thus, pharmacological inhibition of CPT1A with ETO or knockdown of CPT1A expression may block fatty acids-induced tumor promoting effects in colon cancer." (PMID 32913185, 2020). "Given the preferential upregulation of CPT1A by adipocytes, our findings indicate that inhibition of CPT1A may provide an effective approach to block the tumor promoting effects of adipocytes in colon cancer." (PMID 32913185, 2020). "Studies have shown that carnitine palmityl transferase 1A (CPT1A)-mediated fatty acid oxidation (FAO) can help colon cancer cells resist anoikis and thus promote colon cancer metastasis." (PMID 35359956, 2022). "High expression of Carnitine palmitoyltransferase 1A (CPT1A), a key enzyme in FAO, was observed in colon cancer tissues." (PMID 34213835, 2021). "Here, we demonstrated that silencing of CPT1A by iRGD‐exosome‐siCPT1A efficiently suppressed FAO, inhibited tumorigenesis and reversed oxaliplatin resistance in colon cancer." (PMID 34213835, 2021). "Here we demonstrate that carnitine palmitoyltransferase I (CPT1A), a key enzyme controlling fatty acid oxidation (FAO), was upregulated in colon cancer cells upon exposure to adipocytes or fatty acids." (PMID 32913185, 2020). "To examine the effect of fatty acids on CPT1A expression directly, we co-cultured PT130, a patient-derived colon cancer cell line, and SW480 cells with adipocytes." (PMID 32913185, 2020). "Taken together, our findings identify CPT1A-depedent FAO as an essential metabolic pathway that enables the interaction between adipocytes and colon cancer cells." (PMID 32913185, 2020). "Collectively, our data indicate that fatty acids stimulate CPT1A expression to enhance FAO and Wnt signaling mainly through PPARδ activation in colon cancer cells." (PMID 32913185, 2020). "Here we further determined the role of CPT1A, a rate-limiting enzyme required for mitochondrial FAO, in mediating the tumor-promoting effect of adipocytes in colon cancer." (PMID 32913185, 2020). "The transcript levels of CPT1A were lower in most colon cancers (19/24 pairs) than in the adjacent non-tumour tissues." (PMID 39607749, 2024). "In our study, C6orf15 activated the WNT signalling pathway and promoted the nuclear translocation of β-catenin to induce the EMT in colon cancer, and coincidentally, we found an increase in the FAO rate and an increase in the expression of CPT1A after C6orf15 overexpression." (PMID 38654238, 2024). "It lowered pro-inflammatory cytokine levels of IL-1β and TNF-α and enhanced carnitine palmitoyl transferase 1A (CPT1A) and lysophosphatidylcholine acyltransferase 3 (LPCAT3), thereby attenuating the anti-proliferative effect of SIN (2.5 mM) on human colon cancer cells (HT-29, HCT-116, and SW-480)." (PMID 38276618, 2024). "Thus, our experiment used iRGD‐exosome to carry CPT1A siRNA to suppress FAO and reverse oxaliplatin resistance in colon cancer." (PMID 34213835, 2021).
colon cancer (continued). "Lin and colleagues found that carnitine palmitoyltransferase 1A (CPT1A) was more highly expressed in colon cancer tissues than in noncancerous tissues and confirmed that CPT1A was increased by oxaliplatin stimulation in human colon cancer cell lines HCT116 and SW480." (PMID 35814444, 2022). "In addition, we verified that CPT1A was more highly expressed in colon cancer tissues than in noncancerous tissues." (PMID 34213835, 2021). "The upregulation of CPT1A could promote the development of HCC and metastasis of colon cancer." (PMID 33477262, 2021). "However, no research has identified whether CPT1A is related to oxaliplatin resistance in colon cancer." (PMID 34213835, 2021). "The gene and protein expression of enzymes involved in fatty acid catabolism, such as CPT1A, LCAD, and SCAD, did not appear to be consistent in both PT and BR colon cancer cells, especially SCAD." (PMID 34829834, 2021).
metabolic syndrome (25 papers, 2012 to 2026). A cluster of metabolic risk factors for CARDIOVASCULAR DISEASES and TYPE 2 DIABETES MELLITUS. "DNA methylation at cg00574958 in the CPT1A gene region, was associated with lower risk of metabolic syndrome, lipids, BMI and waist circumference, and type 2 diabetes." (PMID 36360196, 2022). "For example, CpGs within CPT1A were associated with the metabolic syndrome and plasma adiponectin, a biomarker for CMD/CVD risk." (PMID 35000590, 2022). "High fructose promotes the methylation levels of PPARα and CPT1A in rat liver, suggesting that DNA methylation status of PPARα and CPT1A is closely associated with the pathogenesis of fructose-induced metabolic syndrome." (PMID 34362460, 2021). "Network analysis identified CPT1A (carnitine palmitoyltransferase 1A) as a master epigenetic locus, acting as a central hub linking dyslipidemia to tumor progression." (PMID 41976360, 2026). "Other associations with cg00574958 in CPT1A have been identified in EWAS of fasting blood lipids, adiponectin, the metabolic syndrome, and cardiovascular disease (CVD) risk." (PMID 33622391, 2021). "Both inhibitors and activators of Cpt1a have been proposed to combat hyperglycemia and the metabolic syndrome." (PMID 23056479, 2012). "Moreover, as a complex mixture of bioactive compounds, it has several additional benefits on energy expenditure (by phosphorylating AMPK) or lipid catabolism (by increasing CPT1a expression) in the aspects of treating dyslipidemia-related complications." (PMID 36826031, 2023). "Collectively, these findings suggest that methylation status of CPT1A may mediate the downstream effects of the metabolic syndrome." (PMID 34183656, 2021). "In the present study, chronic HFD feeding suppressed PPARα activation in the liver, which, in turn, downregulated lipolysis and fatty acid oxidation-related gene levels (LPL, CPT-1a, and ACOX1) and ultimately led to hepatic lipid deposition and dyslipidemia." (PMID 39942052, 2025). "Both CPT1A and CPT1B have significant effects on the metabolic syndrome, cardiovascular disease, type 2 diabetes, and other disorders." (PMID 37033619, 2023).
diabetes (24 papers, 2015 to 2025). "Additionally, 7 CpG sites annotated to MAN2A2, ABCG1, DENND3, NCOR2, BAIAP2 and CPT1A were linked to changes in diabetes status." (PMID 39827095, 2025). "Thus, the importance of NOX4 and CPT1A as molecular targets for therapies aimed at attenuating inflammasome activation has been implicated in diabetes or metabolic diseases." (PMID 30728885, 2019). "The aminocarnitine derivative teglicar (R)-N-(tetradecylcarbamoyl)-aminocarnitine (ST1326), a selective and reversible inhibitor of CPT1A originally used as a drug candidate for diabetes therapy, also plays a central role in the therapy of certain cancers." (PMID 37513899, 2023). "In our study, myocardial Cpt1a expression was higher in offspring exposed to maternal diabetes + HFD (p = 0.041) compared to controls." (PMID 36835096, 2023). "At E10.5, effects of diabetes were significant for Slc27a6/Fatp6, Slc27a4/Fatp4, and Cpt2 (27.8%, 19.4%, and 19.7%, respectively), and for Cpt1a, Slc2a13/Glut13, and Cpt1b, diet was a significant contributor (42.9%, 38.7%, and 31%, respectively)." (PMID 31774824, 2019). "For CPT1A (carnitine palmitoyltransferase 1a), which is a key enzyme of fatty acid transport into mitochondria for beta-oxidation, a link to diabetes or related traits can be found in animal and expression studies." (PMID 27019061, 2016). "Dyslipidaemia and diabetes are closely related, and epigenome-wide approaches have identified differential methylation of genes known to have a key role in lipid metabolism and lipid traits, particularly CPT1A, ABCG1, SREBF1." (PMID 39827095, 2025). "Others demonstrated that diabetes can increase the gene expression of Cpt1a in the heart." (PMID 36835096, 2023). "CPT1A was also lower in lower extremity arterial tissue from individuals with diabetes." (PMID 35783870, 2022). "Finally, the direction of association for CPT1A, ABCG1, SOCS3, TXNIP and SREBF1 was consistent with that reported in the literature for MetS and/or diabetes." (PMID 34780523, 2021). "Interestingly, CPT1A content was lower in arterial segments of patients with diabetes (p < 0.05)." (PMID 35783870, 2022). "We identified significant associations between cg10601624, cg06690548 (SLC7A11), cg19693031 (TXNIP), and cg00574958 (CPT1A) and TOD in the kidney even further after adjustment for BMI, smoking status, and diabetes." (PMID 32917208, 2020). "Notably, among the seven CpG sites liked to the diabetes progression, five showed a negative correlation with gene expression levels, including cg23436042, cg11183227 (MAN2A2), cg06500161 (ABCG1), cg06710464 (BAIAP2), and cg17058475 (CPT1A), while cg08788930 (DENND3) and cg11311053 (NCOR2) did not." (PMID 39827095, 2025).